AR (androgen receptor)
Diseases named in the same sentence as AR in open-access papers (continued):
Sharing a sentence is not in itself a finding about the gene and the disease.
prostate carcinoma (continued). "Aberrant expression of androgen receptor (AR) -dependent transcriptional programs is a decisive pathology in the development of prostate cancer, and studies have shown that TNF-α and TGF-β can be involved in mediating AR-dependent gene transcription." (PMID 35069596, 2021). "HCT and EA induced apoptosis in androgen-sensitive prostate cancer cells (LNCaP) and CRPC cells (PCai1) through activation of caspases, down-regulation of androgen receptor, and inactivation of AKT/ERK/MAPK signaling." (PMID 34298624, 2021). "The cytoplasmic AR binds to several proteins and activates several signaling molecules including SRC, RAS, MAPK, AKT, EGFR, and PI3K among others in prostate cancer." (PMID 33572108, 2021). "These FOXA2-dependent enhancers engage in EP interactions that are specific to tumour cells and influence the expression of key oncogenes, such as the Androgen Receptor (AR) and DLX1 in prostate cancer." (PMID 34298745, 2021). "Here, we have investigated how androgen signaling regulates PARP7 homeostasis in prostate cancer cells, where PARP7 is a direct target gene of AR." (PMID 33572475, 2021). "In prostate cancer (PCa), CHKA is a co-chaperone for the androgen receptor (AR), thus maintains AR signaling." (PMID 34371769, 2021). "ETS binding motifs are enriched at AR occupancy sites in prostate cancer cells, and multiple ETS family members are upregulated in prostate cancer." (PMID 33513133, 2021). "Another research reported that AR/mTOR axis promoted the expression and activity of SREBP1, lead to androgen-dependent de novo synthesis of lipid and facilitated growth of prostate cancer (PCa) cells." (PMID 34041015, 2021). "Prostate cancer arises by the driving of androgens, and the androgen deprivation therapy (ADT) to target the androgen receptor (AR) axis is the mainstay of treatments for metastatic prostate cancer." (PMID 33995674, 2021). "Topics enriched in Samples 4 and 16 include genes such as AR, GRHL2, FOXA1, SLC43A1, WNT7B, which are known downstream players active in prostate cancers with ERG expression." (PMID 34911933, 2021). "We expected that the plants containing the chemicals acting on all three targets, S5R1, S5R2, and AR, can be the new candidates for controlling the symptoms or diseases involving androgen metabolism, such as BPH and prostate cancer." (PMID 33917905, 2021). "The timing and mechanisms of cell death after ADT for prostate cancer are not well understood, and off-target effects after long-term ADT due to functional extra-prostatic expression of the androgen receptor protein are now increasingly being recorded." (PMID 33477370, 2021). "Western blotting revealed that both HCT and EA significantly decreased the expression of AR, p-p38 MAPK, and p-ERK1/2 in both prostate cancer cell lines." (PMID 34298624, 2021). "Recent studies indicated that MARCH6 was positively corrected with androgen receptor (AR) gene expression, which shared common regulation with MARCH6 by the transcription factor Sp1 in prostate cancer." (PMID 34273954, 2021). "In prostate cancer, PIM1S and PIM1L are up-regulated and play a key role in maintaining androgen receptor (AR) stability and transcriptional activity." (PMID 34681783, 2021). "Results from our study further implicate PIM-1 as a key molecule involved in therapeutic resistance to AR and AKT inhibition and provide additional evidence to warrant further investigation of PIM-1 in prostate cancer." (PMID 34439133, 2021). "In the genomic locus of HOXA11-AS, we found androgen receptor (AR)- and forkhead box A1 (FOXA1)-binding sites, which are key components in prostate cancer development and progression." (PMID 33514011, 2021). "Second, EZH2 directly binds to the promoter of prostate-specific antigen, an AR-targeted gene, and inhibits its expression in CAB-resistant prostatic cancer cells." (PMID 35186711, 2021).
prostate carcinoma (continued). "The contribution of the HH-GLI signaling pathway to prostate cancer development as well as interactions of the HH-GLI and AR signaling pathways have been intensely investigated over the past two decades." (PMID 34290270, 2021). "At low physiological doses, the combination of arctigenin and quercetin targeting related pathways (androgen receptor and PI3K/Akt) offers a novel protocol for accelerated chemoprevention in prostate cancer." (PMID 33807174, 2021). "MED19 promotes androgen-independent growth by working with a transcription factor that interacts with AR, called ELK1, to induce the expression of genes regulated by AR that promote prostate cancer growth." (PMID 33513133, 2021). "During synergistic action of quercetin and curcumin, prostate cancer cell lines PC3 and DU145 showed decreased DNMT activity and increased AR expression which induced apoptosis through the mitochondrial pathway." (PMID 34235089, 2021). "We recently showed that chemicals in WBM antagonized dihydrotestosterone (DHT)-induced androgen receptor (AR) activation and PSA expression in prostate cancer cells and animal models." (PMID 34341347, 2021). "In advanced stages of prostate cancer, KDM6A is essential for maintenance of androgen receptor (AR) activity despite anti-androgenic therapy." (PMID 34950587, 2021). "This suggests that MED19 cooperates with ELK1 to regulate AR occupancy and H3K27 acetylation at MAOA, upregulating its expression and driving androgen independence in prostate cancer cells." (PMID 33513133, 2021). "We found that prostate cancer metastasis in bone is prone to have higher prostate-specific antigen (PSA) and longer time on first-line androgen receptor signaling inhibitors (ARSI)." (PMID 33859877, 2021). "For example, AR, PTEN, and ERG expression can vary between different regions within the same prostate carcinoma." (PMID 34638309, 2021). "It is also well established that AR‐repressed BRN2 can induce neuroendocrine differentiation in both castration‐ and enzalutamide‐resistant prostate cancer models." (PMID 33009820, 2021). "In prostate cancer, activated ACK1 promotes tumor growth via androgen receptor (AR) tyrosine phosphorylation, facilitating androgen-independent transactivation of AR and degradation of tumor suppressor WW domain containing oxidoreductase (Wwox)." (PMID 35003030, 2021). "In prostate cancer, NEED4 exerts its oncogenic function by downregulating PTEN and androgen receptor (AR)." (PMID 34458018, 2021). "We describe herein results showing that compared with androgen-dependent prostate cancer (ADPC) cells, AR nuclear translocation capability is enhanced in androgen-independent prostate cancer (AIPC) cells." (PMID 33959503, 2021). "Recent evidence has shown that LGR4 over-expression increased the expression level of the androgen receptor, a transcription factor that controls PSA transcription and plays essential roles in prostate cancer progression." (PMID 33946652, 2021). "Previous findings by our group demonstrated that cabozantinib inhibited the growth of AR-expressing CRPC and altered bone remodeling elicited by prostate cancer cells in vivo." (PMID 33471819, 2021). "The extract showed significant effect on cell viability at the highest tested concentration (400 μg/mL) on most cell lines, excepting estrogen positive MCF-7 breast cancer line and both androgen receptor positive LNCAP and 22RV1 prostate cancer cell lines." (PMID 35009103, 2021). "In prostate cancer, JNK activated by androgen receptor (AR) resulted in elevated MMP-9 levels and cell invasion." (PMID 33671187, 2021). "We also relate its expression to the androgen receptor and MMP-7 protein, both critical to prostate cancer pathogenesis." (PMID 35201496, 2021).
prostate carcinoma (continued). "Therefore, it is compelling to speculate that transcriptional upregulation of PFKFB2 by androgen receptor signaling in hypoxia may represent a potential mechanism by which prostate cancer cells could allosterically upregulate glycolysis in the absence of HIF-1." (PMID 34572020, 2021). "Preclinical studies on prostate cancer cells demonstrated Ki (inhibition constant) of enzalutamide is 86 nM and the IC50 of enzalutamide to suppress widetype AR activation by testosterone based on reporter gene transcription assays is 219 nM." (PMID 34094902, 2021). "In prostate cancer, HOTAIR upregulation promotes cell growth and invasion by blocking the degradation of androgen receptor (AR) protein to which it binds." (PMID 33540611, 2021). "Androgen receptor was also reported to modulate both expression and activity of the TRPM8 channel in a human prostate cancer cell line (PC3)." (PMID 33614639, 2021). "For instance, activated AR has been shown to increase the expression of miR-203 and decrease the expression of SRC kinase in prostate cancer model systems." (PMID 34831421, 2021). "We also reported that PC3 prostate cancer cells and HEK293 human embryonic kidney cells, both of which lack AR, were less sensitive to growth inhibition upon MED19 depletion compared to LNCaP-abl cells." (PMID 33513133, 2021). "In prostate cancer, HOXB13, which is highly expressed in adulthood in the normal prostate, functions as a coregulator of AR, together with FOXA1, to modulate the epigenetic status required for prostate tumorigenesis." (PMID 33514011, 2021). "After treatment with AR antagonists, such as Enzalutamide and Abiraterone, about 10–17% of CRPC patients evolved into neuroendocrinal transdifferentiated prostate cancer, also known as treatment-induced NEPC." (PMID 34572596, 2021). "Although seemingly paradoxical, GHSROS repression of AR and PPP2R2C in prostate cancer cell lines can be rationalized." (PMID 33585078, 2021). "Bergamottin’s role in reducing AR activation was confirmed by confocal microscopy studies and reduction in prostate specific antigen (PSA) levels, which is a marker for prostate cancer." (PMID 34570813, 2021). "The dysregulation of androgen receptor (AR) signaling is a critical event in the progression of prostate cancer (PCa) and hormone therapy consisting of androgen deprivation (ADT) or AR inhibition is therefore used to treat advanced cases." (PMID 34512147, 2021). "In prostate cancer, a key event is the oncogenic activation of transmembrane protease serine 2 (TMPRSS2), via AR signaling." (PMID 34341347, 2021). "In this study, we show that Zeta55 can target both AR and HDAC6, and potently inhibit the tumor growth of prostate cancer in vitro and in vivo." (PMID 33621955, 2021). "The activation of inhibitory pathways of cell proliferation after cetuximab treatment in prostate carcinoma cell lines LNCaP, PC3 and DU145 depends upon androgen receptor status, cell line specific molecular profiles and the occurrence of specific resistances." (PMID 34321039, 2021). "Dynamic aberrations in the androgen receptor, DNA repair genes, PTEN-PI3K, and other pathways drive the behavior of advanced prostate cancer allowing a better selection of therapies in each patient." (PMID 33625671, 2021). "In order to verify the direct effect of huaier extract on the transcriptional activity of AR-FL and AR-V7, we constructed an AR-FL/AR-V7-KLK3-LUC system in AR-negative PC3 prostate cancer cells." (PMID 33708629, 2021). "A phase I trial of EZN‐4176, a second‐generation antisense oligonucleotide to exon 4 of the androgen receptor, has utilized the variations in CTC count to evaluate the drug efficacy in prostate cancer patients." (PMID 33448107, 2021).
prostate carcinoma (continued). "In prostate cancer, TNK2 participates in a feed-forward epigenetic circuit involving ACK1/pY88-H4/WDR5/MLL2/AR and is necessary for malignant cancer." (PMID 34421982, 2021). "MiR-133a-5p inhibited cell proliferation in AR-positive prostate cancer cell line VCaP and LNCaP by targeting both FUS and AR, which further decreased the resistance to androgen ablation therapies." (PMID 33391416, 2021). "CCL2 expression is increased in AR-silenced C4-2 cells, and when AR is suppressed by ADT, prostate cancer-cell-derived CCL2, which mediates a local inflammatory response, plays a major role in tumor progression." (PMID 34445235, 2021). "Multiple lines of evidence from recent research indicate that, in addition to the androgen/AR axis, the tumor microenvironment (TME) plays an indispensable role in prostate cancer initiation and progression." (PMID 33535458, 2021). "Since the discovery of the androgen receptor (AR), ADT has been an indispensable treatment for prostate cancer." (PMID 34103477, 2021). "Since HIP1 decreases androgen receptor degradation, the AR‐PCAL7‐HIP1 axis creates a novel positive feedback loop to advance prostate cancer development." (PMID 33219721, 2021). "These apparent discrepancies between the studies indicate that the extent to which AR-mediated regulation of eIF4F complex assembly and PERK/eIF2α phosphorylation/ISR contributes to translational perturbations in prostate cancer remains to be established." (PMID 34209750, 2021). "Here, the authors identify the writer and reader enzymes for AR ADP-ribosylation and show how they modulate AR signaling output in prostate cancer cells." (PMID 33976187, 2021). "Research found that 41 binds covalently to the AF-1 region of the AR NTD and blocks the proliferation of prostate cancer cells that are dependent on functional AR, and many analogs have been prepared and examined." (PMID 33672769, 2021). "Further study revealed that AR-mediated CPT1B promoted castration-sensitive and castration‐resistant prostate cancer (CRPC) progression by upregulating AKT expression and phosphorylation." (PMID 34706720, 2021). "The clinical observation that castration can restrict prostate cancer development and the development of PSA as a clinical biomarker both reflect AR activity." (PMID 33525365, 2021). "The interactions between miRNAs and AR mRNA, mainly through binding with its 3′UTR, have been mostly assessed in the context of prostate cancer." (PMID 34831421, 2021). "AR and HIF pathways are also predicted to be important targets of XHP in prostate cancer intervention in target prediction, GO function analysis, and gene enrichment analysis." (PMID 35342388, 2021). "PIAS family members promote prostate cancer (PCa) tumorigenesis through the inhibition of CDK p21 levels and modulation of androgen receptor (AR) signaling, which is the most important known growth promoting pathway in PCa." (PMID 34503213, 2021). "Mutations targeting phosphatase and tensin homolog (PTEN) or other components of the PI3K-AKT pathway are often found in prostate cancer and crosstalk between the PI3K-AKT pathway and AR signaling has been described." (PMID 34067046, 2021). "We should note that the AR activation is aligned with human malignancy, such as prostate cancer, HCC, and pancreatic cancer, and that AREs, such as TGF-beta, CCRK, GRP78, and VEGF, play indispensable roles in the AR-mediated carcinogenesis." (PMID 34943942, 2021). "We discovered that the most significantly enriched datasets were for the AR and FOXA1, both of which are important for prostate cancer growth." (PMID 33596994, 2021). "Indeed, steroid hormone receptors including androgen receptor (AR) are members of a superfamily of ligand-activated transcription factors that are potentially oncogenic in gliomas as has been proposed by other researchers and has been confirmed in prostate cancer." (PMID 34094902, 2021).
prostate carcinoma (continued). "Changes in expression of multiple let-7 family members in NE cells correspond with the general function of LIN28 proteins in miRNA biogenesis, while the downstream regulation of AR and Myc by the LIN28B-let-7 axis influences prostate cancer progression." (PMID 34940756, 2021). "In SPOP-mutant prostate cancer, several dysregulated SPOP substrates (e.g., NCOA3, TRIM24, BET proteins) have been shown to boost the AR pathway leading ultimately to high levels of AR target genes 3,13,19–26." (PMID 33531470, 2021). "In prostate cancer, SGK3 is an androgen receptor transcriptional target and promotes cancer cell proliferation." (PMID 33613114, 2021). "In prostate cancer, FKBP51 and FKBP52 promoted cell proliferation by regulating AR’s nuclear translocation and dimerization." (PMID 34831344, 2021). "In localized primary human prostate cancer samples from the TCGA cohort, we observed that KIF4A and AR gene expression are correlated." (PMID 34326322, 2021). "While the role of SPOP protein differs depending on the tumor type, in prostate cancer, SPOP seems to function as a tumor suppressor and its targets for degradation, among others, include AR, ERG, steroid receptor coactivator 3 (SRC3), BRD4, MYC, and TRIM24." (PMID 33572160, 2021). "The prominent pathology in prostate cancer is adenocarcinoma; however, in rare cases (<1%), NEPC tumors occur and present with an AR-null phenotype." (PMID 35127483, 2021). "Prostate specific antigen (PSA) is a serine protease produced by prostate epithelial cells and prostate cancer (PCA), which can be regulated by AR." (PMID 33981239, 2021). "Enzalutamide, an AR inhibitor approved for use in CRPC patients, can reduce TMPRSS2 expression in prostate cancer cells." (PMID 33558541, 2021). "Further, AR and EMT regulator β-catenin were localized to the nucleus, suggesting that the crosstalk between TGF-β signaling, AR, and EMT mediate progression of prostate cancer to CRPC." (PMID 33076397, 2020). "For example, AR, EGFR, DDR2 and MAP2K2 were connected with mtDNA genes in prostate cancer, and TMPRSS2, NF1, PIK3CA, BRCA1 and TOP1 were the top neighbors of mtDNA genes in multiple cancer types." (PMID 32024997, 2020). "Derived from an omental fat metastasis of a prostate carcinoma exhibiting a major small-cell/neuroendocrine component, the LuCaP49 PDX model lacks expression of PSA and AR and is characterized by insensitivity to androgen deprivation and rapid tumor growth." (PMID 32313004, 2020). "In prostate cancer, FOXA1 is indispensable in androgen receptor (AR)-mediated gene regulation by interacting directly with AR and co-occupying chromatin." (PMID 32929382, 2020). "In prostate cancer, SMYD3 elicits its oncogenic activity by stimulating androgen receptor (AR) transcription." (PMID 31935919, 2020). "In the present study, we showed the anti-cancer effects of H. abdominalis and its bioactive compound, brassicasterol, on AR and AKT expression in prostate cancer cells." (PMID 32972001, 2020). "One other example of the clinical relevance of AR and ERG chromatin loops is the link detected between a prostate cancer GWAS SNP, rs9364554, located in the intron of SLC22A3 within an AR and ERG loop anchor." (PMID 32634370, 2020). "Apart from being a biomarker of choice for prostate cancer, PSA is an AR-dependent gene and therefore constitutes a good candidate to verify AR activity as a transcription factor." (PMID 33207735, 2020). "Our study investigated the role and mechanism of cir-ITCH in PCa and provided evidence indicating that cir-ITCH functions as tumor suppressor in prostate cancer cells via the Wnt/β-catenin and PI3K/AKT/mTOR pathways in an AR-independent manner." (PMID 32904490, 2020). "Our findings suggest that SHL has the anticancer potential via inhibition of AR and demonstrated that brassicasterol from H. abdominalis exerted an anti-cancer effect by dual-targeting AKT and AR signaling in prostate cancer." (PMID 32972001, 2020).